ANXA1 (annexin A1)
Diseases named in the same sentence as ANXA1 in open-access papers (continued):
Sharing a sentence is not in itself a finding about the gene and the disease.
edema (1 paper, 2021). An abnormal accumulation of fluid beneath the skin, or in one or more cavities of the body. "However, the addition of the anti-AnxA1 antibody or BOC2 significantly blocked the protective effects of 2ME on IR-induced lung edema." (PMID 33796096, 2021).
epithelial dysplasia (1 paper, 2022). "In addition, our results unprecedentedly revealed the clinical utility of ANXA1 for early and accurate detection of epithelial dysplasia, since ANXA1 loss occurred in early tumorigenesis and was detected in all dysplastic precancerous lesions." (PMID 36247003, 2022). "Of great interest and application, results revealing ANXA1 lost as an early marker to facilitate histopathological diagnosis of epithelial dysplasia." (PMID 36247003, 2022).
Erythema (1 paper, 2019). Redness of the skin, caused by hyperemia of the capillaries in the lower layers of the skin. "The AnxA1-/- AD group exhibited skin with intense erythema, erosion and dryness associated with increased skin thickness compared to the AD WT group." (PMID 30650525, 2019).
fibroma (1 paper, 2022). A non-metastasizing neoplasm arising from the fibrous tissue. "Accordingly, archived paraffin-embedded biopsy samples were subjected to immunohistochemistry to establish tissue localization and profile of GILZ and Annexin A1 coupled with the use of hematoxylin–eosin stain for histopathological assessment; for comparison, fibroma specimens served as controls." (PMID 35563776, 2022). "All sections of fibromas showed positive Annexin A1 nuclear staining in the epithelium, while additional cytoplasmic and cellular membrane staining was observed in some of the epithelial cells in a patchy distribution; however, for most sections, the basal layer(s) showed minimal or no stain." (PMID 35563776, 2022). "This study shows an abundant expression of GILZ and Annexin A1 in oral biopsy specimens of humans, with heterogeneous demographics and histopathological diagnosis of OC, OLP, or fibroma." (PMID 35563776, 2022). "Further, we observed a significant reduction in normalized staining for GILZ, but not Annexin A1, for OLP and OC compared to fibroma." (PMID 35563776, 2022). "In conclusion, despite heterogeneous demographics, staining patterns for GILZ and Annexin A1 in the oral mucosal epithelium of human subjects did not differentiate the inflammatory conditions of OLP and OC from the fibroma." (PMID 35563776, 2022).
fragile X syndrome (1 paper, 2014). A genetic syndrome caused by mutations in the FMR1 gene which is responsible for the expression of the fragile X mental retardation 1 protein. "Abnormal post-translational processing of ANXA1 has been previously observed in individuals with Fragile X syndrome, which frequently presents with autistic symptomatology." (PMID 24720851, 2014).
galactosaemia (1 paper, 2018). "The expression of ANXA1 and ICAM1 expression correlated strongly in galactosaemia patients (rs = 0.624, p < 0.05 × 10− 4), suggesting an inflammatory association." (PMID 30231941, 2018). "We studied two genes as possible anti-inflammatory markers, ANXA1 and ICAM1, the former which we previously reported as dysregulated in galactosaemia." (PMID 30231941, 2018).
gastric tumors (1 paper, 2014). "In tumor, however, loss of ANXA1 expression was observed in 31 (59.6%) of the 52 primary gastric tumors." (PMID 25038797, 2014). "Immunohistochemical analysis revealed a higher expression of COX-2 and a lower expression ANXA1 in gastric tumors than those in non-cancerous tissues." (PMID 25038797, 2014).
gastrointestinal carcinomas (1 paper, 2014). "These differentially expression patterns of ANXA1 in gastrointestinal carcinomas set a solid groundwork for further ANXA1-targeted molecular cancer therapy and as a diagnostic and prognostic marker." (PMID 25038797, 2014).
hemangioma (1 paper, 2024). A benign vascular lesion characterized by the formation of capillary-sized or cavernous vascular channels. "Recent studies have revealed that ANXA1 may be related to capillary formation in infant hemangiomas, suggesting that ANXA1 plays an important role in maintaining a normal vessel density." (PMID 38358087, 2024).
hemoglobinopathies (1 paper, 2016). "ANXA1 and proinflammatory cytokines were quantified by ELISA in plasma of SCD patients and control individuals without hemoglobinopathies." (PMID 27802331, 2016).
Hepatic steatosis (1 paper, 2019). Steatosis is a term used to denote lipid accumulation within hepatocytes. "Collectively, our findings suggest that ANXA1 reduces the development of hepatic steatosis and the associated liver injury by inhibition of RhoA activity and restoration of IRS-1 signaling." (PMID 30972066, 2019).
hilar cholangiocarcinoma (1 paper, 2014). A cholangiocarcinoma that arises from the junction, or adjacent to the junction, of the right and left hepatic ducts. "In hilar cholangiocarcinoma, ANXA1 mRNA changed a little, but ANXA1 protein was sharply down-regulated compared with surrounding noncancerous tissue revealed by immunohistochemical analysis (D and 2 first panel)." (PMID 25038797, 2014).
Hyperinsulinemia (1 paper, 2013). An increased concentration of insulin in the blood. "Although hyperinsulinemia was previously reported in male C57BL6 ANXA1 KO mice on chow diet, in our study chow-fed female Balb/c ANXA1 KO mice only showed a non-significant trend towards elevated plasma insulin, a discrepancy likely attributable to strain- and sex-specific differences." (PMID 24312665, 2013).
immune deficiency (1 paper, 2024). "Higher frequencies of these cells in wildtype mice indicate a potential immune deficiency caused by the absence of ANXA1." (PMID 39076982, 2024).
inflammatory skin disease (1 paper, 2019). Inflammatory skin disorders covers a broad category that includes many conditions ranging in severity, from mild itching to grave medical health complications These disorders are common in people of all ages and races. "Our results suggest AnxA1 as an important therapeutic target for inflammatory skin diseases." (PMID 30650525, 2019).
intrauterine growth restriction (1 paper, 2025). "Meanwhile, studies have shown that ANXA1 is associated with intrauterine growth restriction (IUGR) in rat models." (PMID 40551992, 2025).
invasive carcinoma (1 paper, 2006). A carcinoma that is not confined to the epithelium, and has spread to the surrounding stroma. "For three of them (cadherin 11, annexin A1, and vimentin), we observe the same expression pattern as published by Nagaraja and colleagues for the transition from in situ to invasive carcinoma." (PMID 17069663, 2006).
iron overload (1 paper, 2024). "However, the overall link between ANXA1, IL-17, astrocyte activation and iron overload in chronic pruritus is unknown." (PMID 38790419, 2024).
itch (1 paper, 2024). "Collectively, these specific findings imply that the inhibitory effects of ANXA1 on ACD-induced chronic itch might be associated with reducing IL-17-mediated astrocyte activation and TfR1-caused iron accumulation in the dorsal horn of the spinal cord." (PMID 38790419, 2024).
kidney (1 paper, 2021). "For example, with respect to acute kidney injury simulated by ischemia reperfusion injury, treatment with either Annexin A1 peptide mimetics or the cell-permeable GILZ protein exert marked renoprotection." (PMID 34943928, 2021).
kidney cancer (1 paper, 2021). Primary or metastatic malignant neoplasm involving the kidney. "With respect to kidney cancer, early recognition of Annexin A1-mediated growth inhibition of glucocorticoids in human lung adenocarcinoma cell line led to the determination of the impact of hydrocortisone and hrANXA1 on cultured human mesangial cells (CHMC)." (PMID 34943928, 2021). "Accordingly, expression of Annexin A1 was assessed in fetal kidneys (at different gestational periods), mature kidneys and in kidney cancer tissues to gain insight into its localization and its potential role during nephrogenesis and in renal tumors." (PMID 34943928, 2021).
lentivirus infection (1 paper, 2024). Virus diseases caused by the Lentivirus genus. "To determine whether the increased expression of p15 induced by ANXA1 knockdown was mediated by NICD signals, we constructed stable NICD over‐expression and Notch1 knockdown cell lines by lentivirus infection." (PMID 39447086, 2024).
Lewis Lung carcinoma (1 paper, 2013). "One study suggested that ANXA1 appears to be induced in tumor endothelium, and the lack of ANXA1 in ANXA1-KO mice may impair tumor-induced angiogenesis with reduced blood supply explaining retarded tumor growth and metastasis in Lewis Lung carcinoma." (PMID 23341933, 2013).
lipodystrophy (1 paper, 2022). A congenital or acquired disorder characterized by abnormal loss or redistribution of the adipose tissue in the body. "Plasma annexin A1 levels were decreased in patients with lipodystrophy compared to BMI matched controls (0.2 ± 0.1 ng/mL, n = 9 vs. 0.97 ± 0.1 ng/mL, n = 30, p = 0.008), whereas CRP levels were significantly elevated (3.3 ± 1.0 μg/mL, n = 9 vs. 1.4 ± 0.3 μg/mL, n = 31, p = 0.0074)." (PMID 35684160, 2022). "Interestingly, the average plasma levels of ANXA1 were significantly lower in lipodystrophy patients compared to control (0.2 ± 0.1 ng/mL, n = 9 vs. 0.97 ± 0.1 ng/mL, n = 30, p = 0.008)." (PMID 35684160, 2022). "The attenuated ANXA1 levels observed in lipodystrophy patients with low adiposity and in obese participants with high adiposity may therefore result from an increased systemic inflammatory environment where the balance of inflammation is tipped in favour of pro-inflammatory factors." (PMID 35684160, 2022). "Furthermore, the data presented from lipodystrophy patients suggest that plasma ANXA1 levels are not related to morphology per se, but are correlated with a pro-inflammatory environment." (PMID 35684160, 2022).
liposarcoma (1 paper, 2007). A usually painless malignant tumor that arises from adipose tissue. "Genes highly expressed in the dedifferentiated/pleomorphic liposarcomas included cell-cycle genes like CCNA2, CCNB2, CDC2, KIFC1, KIF23 and PTTG1, motility genes like AMFR, ANXA1, CKB, CNN2 and FN1 and homeostasis-related genes." (PMID 17359542, 2007).
malaria (1 paper, 2013). Malaria is a serious and sometimes fatal disease caused by a parasite that commonly infects a certain type of mosquito which feeds on humans. "The aim of this study was to investigate the annexin-A1 expression in CD4+, CD8+ T cells, regulatory T cells (Treg) and cytokine IL-10 quantification in plasma from patients with malaria caused by P. vivax." (PMID 24359168, 2013). "The endogenous protein ANXA1 expression in circulating lymphocytes subpopulations of patients with malaria P. vivax and from healthy individuals was performed by immunofluorescence." (PMID 24359168, 2013). "It was also observed a positive relation between ANXA1 expression and the number of previous episodes of malaria in CD4+ T cells." (PMID 24359168, 2013). "Also, the ANXA1 expression in lymphocytes was analysed according to the number of previous episodes of malaria." (PMID 24359168, 2013). "Therefore, the aim of this study was to investigate the expression of ANXA1 in CD4+, CD8+ T cells, regulatory T cells (Treg) and quantification of the cytokine IL-10 in plasma from patients with malaria caused by P. vivax." (PMID 24359168, 2013). "Also, it is important to highlight that high ANXA1 expression in some lymphocytes and other leukocytes might had influence on the levels of IL-10 in malaria patients." (PMID 24359168, 2013). "Therefore, the evaluation of IL-10 and ANXA1 in the individuals with malaria was performed." (PMID 24359168, 2013).
male infertility (1 paper, 2021). The inability of the male to effect fertilization of an ovum after a specified period of unprotected intercourse.
metastatic cancers (1 paper, 2018). A carcinoma which has spread from the original site of growth to another anatomic site. "An siRNA knock-down of ANXA1 in the B16B16 cells reduced their invasive capability giving rise to idea that ANXA1 could also be a potential therapeutic target for metastatic cancers." (PMID 29614751, 2018).
metastatic colorectal cancer (1 paper, 2019). "Serum annexin A1 levels were unchanged in metastatic colorectal cancer subjects compared with healthy blood donors." (PMID 31545917, 2019).
muscular dystrophy (1 paper, 2023). Muscular dystrophy (MD) refers to a group of more than 30 genetic diseases characterized by progressive weakness and degeneration of the skeletal muscles that control movement. "Co-immunoprecipitation has revealed that annexin-A1 associates with dysferlin in a calcium- and membrane-injury-dependent manner, a behavior consistent with reported involvement of multiple annexins in muscle repair and muscular dystrophy (e.g., annexin A11)." (PMID 36902136, 2023).
myxoma (1 paper, 2024). A benign soft tissue neoplasm characterized by the presence of spindle and stellate cells, lobulated growth pattern, and myxoid stroma formation. "The communication between macrophages and myxoma cells involved several signaling pathways reported to promote macrophage M2-like polarization, such as ANGPT, ANNEXI, ANXA1, VISFATI, and GAS signaling pathways 53,54and tumor growth-promoting pathways, such as EGF and PDGF signaling pathways 55,56." (PMID 39090109, 2024).
Neonatal sepsis (1 paper, 2013). Systemic inflammatory response to infection in newborn babies. "In the present study, we investigated the level of annexin A1 during the first 24 hrs following A. baumannii infection, and cytokines determined from prior study were in patient hospitalized for neonatal sepsis." (PMID 24369483, 2013).
ocular infections (1 paper, 2022). "Increased expression of AnxA1 and fpr2, mediators in homeostasis of inflammation and ocular infections in infected mice, was observed and further investigations on the use of AnxA1 as a possible co-adjuvant therapeutic strategy in bacterial keratitis were suggested." (PMID 35328532, 2022).
Osteopenia (1 paper, 2019). Osteopenia is a term to define bone density that is not normal but also not as low as osteoporosis. "Thus, a change in the balance of T cell osteoclastogenic activity, arising from the reduced annexin A1 mRNA levels in PBMCs from osteopenia/osteoporosis patients, could contribute to their osteopenia/osteoporosis." (PMID 31814858, 2019). "The levels of mRNAs of annexin A1, S100A4, and TMEM64 in human peripheral blood mononuclear cells were evaluated among 48 osteopenia and 23 osteoporosis patients compared to 17 nonosteoporotic controls." (PMID 31814858, 2019). "Thus, the aim of this study was to find out whether the levels of mRNAs for annexin A1, S100A4, and TMEM64 were significantly changed in the PBMCs of participants with osteopenia or with osteoporosis compared to nonosteoporotic controls." (PMID 31814858, 2019).
osteoporosis (1 paper, 2019). A condition of reduced bone mass, with decreased cortical thickness and a decrease in the number and size of the trabeculae of cancellous bone (but normal chemical composition), resulting in increased fracture incidence. "This study is aimed at investigating the level of calcium-binding/associated proteins, annexin A1, S100A4, and TMEM64, in peripheral blood mononuclear cells associated with osteoporosis and its clinical significance." (PMID 31814858, 2019). "ROC analysis showed that the reduction in the level of mRNA for annexin A1, S100A4, or TMEM64 in the patients' peripheral blood mononuclear cells has a good diagnostic value for osteoporosis." (PMID 31814858, 2019). "The results show for the first time that calcium-binding/associated proteins, annexin A1 and TMEM64, could be future diagnostic biomarkers for osteoporosis." (PMID 31814858, 2019). "Three mRNAs, encoding calcium-binding/associated proteins, ANXA1, S100A4, and TMEM64, were found to be at a lower level in the PBMC preparations from osteoporosis patients than nonosteoporotic controls." (PMID 31814858, 2019). "The levels of mRNAs for annexin A1, S100A4, and TMEM64 were reduced in PBMCs from osteoporosis patients compared to nonosteoporotic controls; thus, the presence of these mRNAs marked the nonosteoporotic condition." (PMID 31814858, 2019). "Annexin A1 and TMEM64 mRNAs were also significantly reduced in female osteoporosis patients over the age of 50 years compared to nonosteoporotic controls (one-way ANOVA, P = 0.004 and P = 0.0037, respectively)." (PMID 31814858, 2019).
penile cancer (1 paper, 2013). A primary or metastatic malignant neoplasm that affects the penis. "Other recent investigation showed that strong cellular and cell surface expression of ANXA1 in tumor cells at the invasion front was significantly associated with the occurrence of metastasis in penile cancer." (PMID 23341933, 2013). "Furthermore, it is the first time in the literature that ANXA1 protein overexpression is associated with HPV related penile cancer." (PMID 23341933, 2013). "So, probably ANXA1 might have an oncogenic role in penile cancer with high-risk HPVs." (PMID 23341933, 2013). "ANXA1 and p16 proteins were significantly more expressed in the cells from high-risk HPV-positive penile carcinoma as compared to HPV-negative tumors (p<0.0001) independently of the subtype of the carcinoma." (PMID 23341933, 2013). "The RaSH approach identified differential expression of Annexin A1 (ANXA1), p16, RPL6, PBEF1 and KIAA1033 in high-risk HPV positive penile carcinoma; ANXA1 and p16 were overexpressed in penile squamous cells positive for high-risk HPVs compared to normal penile samples by qPCR." (PMID 23341933, 2013).
Plasmodium vivax malaria (1 paper, 2013). Malaria resulting from infection by Plasmodium vivax. "Furthermore, annexin-A1 may be contributing to IL-10 release in plasma of patients with vivax malaria." (PMID 24359168, 2013). "Furthermore, ANXA1 may be contributing to IL-10 production in plasma of patients with vivax malaria." (PMID 24359168, 2013).
Pleuritis (1 paper, 2019). Inflammation of the pleura. "In addition, pre-treatment of mice with AnxA1 in OVA-induced pleuritis has been shown to significantly increase the number of intact mast cells in the pleural fluid and, in vitro, decrease histamine release." (PMID 30650525, 2019).
pneumococcal meningitis (1 paper, 2020). An acute purulent infection of the meninges and subarachnoid space caused by Streptococcus pneumoniae, most prevalent in children and adults over the age of 60. "Here, we investigated the effects of the annexin A1 mimetic peptide Ac2-26 in a mouse model of pneumococcal meningitis." (PMID 33121515, 2020).
pneumoconiosis (1 paper, 2024). An occupational lung disorder caused by inhalation of dust particles. "SPP1 and ANXA1 is associated with pneumoconiosis and they may be the disease biomarkers." (PMID 39283905, 2024).
promyelocytic leukemia (1 paper, 2019). "Annexin A1 upregulation has been also reported to be involved in resveratrol-induced apoptosis of human promyelocytic leukemia HL-60 cells." (PMID 31861640, 2019).
psoriasis vulgaris (1 paper, 2014). Plaque psoriasis is the most common presentation of psoriasis. "Relative values of serum ANXA1 levels ranged from 165.5 to 4041.0 (median: 772.6), 287.0 to 1591.0 (median: 821.3), and 226.0 to 1704.0 (median: 706.4) in patients with psoriasis vulgaris, psoriatic arthritis, and in healthy controls, respectively." (PMID 25010044, 2014). "Two proteins each, moesin and K17 for psoriasis vulgaris, and STIP1 and ANXA1 for psoriatic arthritis, were selected for further experiments, because the expression levels of these proteins were more than twice those in healthy controls." (PMID 25010044, 2014).